NSUN2 (NOP2/Sun RNA methyltransferase 2)
Diseases named in the same sentence as NSUN2 in open-access papers (continued):
Sharing a sentence is not in itself a finding about the gene and the disease.
gastric cancer (continued). "Nevertheless, we also treated the cells with RSL3, a classical ferroptosis inducer, and consistent results as Dox treatment were also acquired, suggesting that lactate-mediated NSUN2 lactylation could protect gastric cancer cells from Dox or RSL3-induced ferroptosis." (PMID 39742570, 2025). "In gastric cancer (GC), methylation sequencing and RT-qPCR confirmed that knocking out NSUN2 significantly decreased PIK3R1 and PCYT1A expression levels." (PMID 41462962, 2025). "Meanwhile, NSUN2 promotes not only the proliferation and metastasis of gastric cancer (GC) cells but also the occurrence and development of esophageal squamous cell carcinoma (ESCC) and gallbladder carcinoma (GBC)." (PMID 37769000, 2023). "Furthermore, NSUN2 was also found to promote migration in gastric cancer cells." (PMID 35350378, 2022). "Our findings suggested that NSUN2 acted as an oncogene through promoting gastric cancer development by repressing p57Kip2 in an m5C-dependent manner, which may provide a novel therapeutic target against gastric cancer." (PMID 32332707, 2020). "In summary, we found that NSUN2 acted as an oncogene through promoting gastric cancer development by repressing p57Kip2 in an m5C-dependent manner, which may provide a novel therapeutic target against gastric cancer." (PMID 32332707, 2020). "Furthermore, NSUN2 could promote gastric cancer cell proliferation by repressing p57Kip2 in an m5C-dependent manner." (PMID 32332707, 2020). "Our results indicated that NSUN2 could promote human gastric cancer tumorigenesis in vivo." (PMID 32332707, 2020). "However, the role and potential mechanism of NSUN2 in gastric cancer remains to be determined." (PMID 32332707, 2020). "Omental adipocytes provide fatty acids to peritoneal metastatic gastric cancer cells, thereby activating the AMPK signaling pathway to augment transcription factor E2F1 expression, which in turn upregulates NSUN2." (PMID 41522342, 2026). "The NSUN2-mediated m5C modification subsequently promotes GCLC accumulation, thereby protecting gastric cancer cells from ferroptosis." (PMID 41413017, 2025). "NSUN2 also increases Netrin 1(NTN1) expression and stabilizes NTN1 mRNA by enhancing m5C modification, affecting gastric cancer cell migration and NI potential." (PMID 39791162, 2025). "Similarly, in gastric cancer (GC), NSUN2 is significantly upregulated in both GC tissues and cell lines." (PMID 41256859, 2025). "Recent studies demonstrate that NAA10-mediated lactylation of NSUN2 at residues K216 and K389 depletes glutathione levels and compromises GPX4 activity, thereby conferring resistance to ferroptosis in gastric cancer cells." (PMID 41480383, 2025). "Mechanistically, the methyltransferase activity of NSUN2 and m5C modification in the 3’-UTR region of p57Kip2 mRNA disrupts its stability, thereby facilitating gastric cancer progression." (PMID 40370440, 2025). "In bladder cancer, NSUN2 methylates and stabilizes HDGF mRNA 3′UTR (also stabilized by METTL3 in gastric cancer) promoting cancer metastasis." (PMID 37369946, 2023). "NSUN2 promoted gastric cancer development was promoted by CDKN1C repression, and the knockdown of NSUN2 suppressed tumor growth." (PMID 37700248, 2023). "For example, the RNA methyltransferase NSUN2 is recruited by FOXC2-AS1 to FOXC2 mRNA, elevating its m5C level and boosting its interaction with YBX1 to control gastric cancer onset and progression." (PMID 37670275, 2023). "In gastric cancer (GC) cells, a small ubiquitin-like modifier (SUMO)-2/3 interacts with the NSUN2 protein to promote its stability and mediate its import into the nucleus." (PMID 35562754, 2022). "Additionally, in gastric cancer (GC), NSUN2 modifies the 3'UTR of cyclin-dependent kinase inhibitor 1C (CDKN1C, p57Kip2) mRNA to repress its stability, decreasing the half-life of p57Kip2 mRNA." (PMID 35562754, 2022).
gastric cancer (continued). "Also, to reduce the stability of p57 mRNA in gastric cancer, the NSUN2 is responsible for the m5C methylated sites on the 3’ -untranslated regions of p57, thus suppressing the expression of p57, which may lead to the development of gastric cancer." (PMID 35937999, 2022). "Moreover, NSUN2 could promote gastric cancer cell proliferation both in vitro and in vivo." (PMID 32332707, 2020). "Moreover, NSUN2 could promote the gastric cancer cells proliferation both in vitro and in vivo." (PMID 32332707, 2020). "Moreover, lactylation upregulates the catalytic activity of NSUN2, leading to enhanced m5C modification and stability of GCLC mRNA, which promotes GSH synthesis and ultimately protects gastric cancer cells from ferroptosis." (PMID 41522342, 2026). "Studies indicate that NSUN2 expression is upregulated in gastric cancer compared to adjacent non-cancerous tissues." (PMID 40370440, 2025). "NSUN2 boosts ORAI2 mRNA stability through m5C modification and enhances ORAI2 expression via YBX1 recognition, promoting peritoneal metastasis and the spread of gastric cancer." (PMID 39791162, 2025). "The expression of NONO and some m5C-related genes was positively correlate in gastric cancer, and the strongest correlation was NSUN2, and the expression of these genes were increased compared with normal gastric tissue." (PMID 40033337, 2025). "NSUN2 activates the ORAI2 expression, promoting gastric cancer metastasis." (PMID 38468490, 2024). "Similar to previous studies, NSUN2 was indeed highly expressed in gastric cancer, ESCC and nasopharyngeal carcinoma, which indicated that NSUN2 might be highly expressed in other tumor types and can be used as a potential pan-cancer biomarker." (PMID 37769000, 2023). "However, the biological significance of NSUN2 in gastric cancer (GC) and the modification of NSUN2 itself have not been fully investigated." (PMID 34504059, 2021). "NSUN2 is an important m5C writer that plays an important role in various cancers, including esophageal squamous cell carcinoma (ESCC), urothelial carcinoma of the bladder (UCB), gastric cancer (GC), hepatocellular carcinoma, and osteosarcoma." (PMID 39340806, 2024). "However, the role and related mechanisms of NSUN2 in gastric cancer has not been investigated." (PMID 32332707, 2020).
hepatocellular carcinoma (34 papers, 2020 to 2026). A malignant tumor that arises from hepatocytes. "A recent significant study found that NSUN2 is significantly upregulated in hepatocellular carcinoma (HCC), and its high expression is closely associated with poor prognosis in HCC patients." (PMID 40370440, 2025). "m5C writer NSUN2 acts as an oncogene to promote gastric cancer and hepatocellular carcinoma (HCC) development by regulating protein-encoding gene CDKN1C and lncRNA H19, respectively." (PMID 36806253, 2023). "Another study demonstrated that NSUN2-deficient hepatocellular carcinoma cells were less in G1 and S phases, compared to G0 and G2 phases, indicating that inhibition of the NSUN2 gene significantly suppressed proliferation and division of HepG2 cells." (PMID 37045913, 2023). "The Kaplan–Meier survival curve showed that the patients with hepatocellular carcinoma in the high-risk group and those with NSUN2, NUDT3 and LARP1 genes in the high expression group had a lower survival rate and shorter survival time." (PMID 36335189, 2022). "Abnormal m5C modification of lncRNA H19 mediated by NSUN2 was associated with poor differentiation of hepatocellular carcinoma." (PMID 34917609, 2021). "In this study, we constructed an NSUN2-deficient hepatocellular carcinoma cell line and investigated the effect of NSUN2 on cell proliferation, migration, and invasion in vitro and in vivo." (PMID 32978516, 2020). "To further determine whether NSUN2 deficiency inhibits tumorigenicity in hepatocellular carcinoma in vivo, we established a xenograft model by inoculating nude mice with NSUN2-deficient HepG2 cells." (PMID 32978516, 2020). "In hepatocellular carcinoma (HCC), upregulation and increased m5c methylation by NSUN2 are associated with poor differentiation of cancer cells." (PMID 40243425, 2025). "It has been recently reported the role of novel genes in driving hepatocellular carcinoma progression, such as Floittillin‐1 regulated Golgi homeostasis, NSUN2‐mediated immune evasion." (PMID 41578084, 2026). "In conclusion, this study revealed that NSUN2-mediated m5C modification promotes glycolysis and the progression of hepatocellular carcinoma by stabilizing PKM2 mRNA, and provides a potential prognostic factor and therapeutic target for HCC patients." (PMID 39924557, 2025). "NSUN2 promotes the progression of lung cancer and hepatocellular carcinoma by affecting cellular metabolism." (PMID 41256854, 2025). "In hepatocellular carcinoma, NSUN2 acted as an oncogene by methylating lncRNA H19, which then bound to G3BP1, promoting its stabilization, thereby leading to carcinogenesis." (PMID 39340806, 2024). "For example, the m5C modification mediated by NSUN2 promotes poor differentiation in hepatocellular carcinoma (HCC)." (PMID 37769000, 2023). "There have been reported that NSUN2 exerted its functions by regulating lncRNA m5C methylation in esophageal squamous cell carcinoma, hepatocellular carcinoma and cholangiocarcinoma." (PMID 37582794, 2023). "In the progression and malignancy of hepatocellular carcinoma, NSUN2-mediated m5C modification of H19 lncRNA plays an important role in the process of mutation of the lncRNA." (PMID 37542290, 2023). "In hepatocellular carcinoma, NSUN2 methylates and increases the stability of the tumor-related lncRNA H19. m5C-methylated H19 correlates to poor hepatocellular carcinoma differentiation." (PMID 36969033, 2023). "In hepatocellular carcinoma, NSUN2 affects the biological function of hepatocellular carcinoma cells and methylates lncRNA H19RNA and methylated H19 recruits oncogene G3BP1 to promote the occurrence and development of tumors." (PMID 35574373, 2022). "NSUN2 is the most studied m5C methyltransferase and participates in various cancers, such as bladder cancer, gallbladder carcinoma, and hepatocellular carcinoma." (PMID 35281843, 2022). "Another research showed that NSUN2 promoted the occurrence and development of hepatocellular carcinoma through m5C modification." (PMID 35978830, 2022).
hepatocellular carcinoma (continued). "In hepatocellular carcinoma, NSUN2 expression is increased, and H19 lncRNA stability is maintained to promote cancer development." (PMID 35433474, 2022). "In conclusion, our results revealed that the NSUN2-mediated m5C modification of H19 lncRNA exert an important function in the progression and malignancy of hepatocellular carcinoma." (PMID 32978516, 2020). "In the present study, we found that depletion of NSUN2 led to inhibition of the proliferation, migration, and invasion of hepatocellular carcinoma cells in vitro." (PMID 32978516, 2020). "Furthermore, we found that NSUN2 promoted cell proliferation in GC cells and promoted migration and invasion in various human tumor cells, including GC, breast cancer, hepatocellular carcinoma, thyroid cancer, and esophageal cancer." (PMID 34504059, 2021). "Furthermore, we provide a landscape of NSUN2-mediated m5C modification in hepatocellular carcinoma cells, and identified H19 lncRNA as a target of NSUN2." (PMID 32978516, 2020). "For example, in hepatocellular carcinoma (HCC), NSUN2 promotes cell proliferation, migration, and tumor growth, while in cervical cancer, NSUN2 increases the m5C modification of LRRC8A, thereby inhibiting apoptosis and promoting cisplatin resistance." (PMID 41463199, 2025). "For example, in hepatocellular carcinoma (HCC), studies have shown that the overall m5C modification level is significantly higher in tumor tissues compared to adjacent normal tissues, and NSUN2 is highly expressed in HCC." (PMID 41256859, 2025). "In sorafenib-resistant hepatocellular carcinoma (HCC), NSUN2 cooperates with ALYREF to maintain the stability and high expression of the long non-coding RNA MALAT1 via its m5C methyltransferase activity." (PMID 41256859, 2025). "reveled that NSUN2, an m5C methyltransferase, is significantly upregulated in hepatocellular carcinoma (HCC), and it promotes tumor progression by catalyzing the H19 lncRNA methylation-mediated recruitment of the G3BP1 oncoprotein." (PMID 36777349, 2023). "In hepatocellular carcinoma (HCC), m5C-related RNA methyltransferase NSUN2 targets lncRNA H19 and stabilizes its expression." (PMID 34777473, 2021). "The “writer” NSUN2 modifies the lncRNA H19 and recruits the oncoprotein G3BP1 in hepatocellular carcinoma, suggesting that m5C modifications are involved in malignant tumor progression." (PMID 37666951, 2023). "Finally, analysis of TCGA database revealed that the combined high expression of NSUN2, YBX1 and QSOX1 predicted the poorest overall survival in lung adenocarcinoma (LUAD), breast cancer (BRCA) and hepatocellular carcinoma (HCC)." (PMID 37161388, 2023).
breast cancer (33 papers, 2017 to 2025). A primary or metastatic malignant neoplasm involving the breast. "It was reported that NSUN2 expression was associated with tumor stage and pathological subtype of breast cancer." (PMID 35721510, 2022). "DNA hypomethylation has also been found to be associated with increased NSUN2 expression in breast cancer, and NSUN2 overexpression promoted cell proliferation, migration, and invasion while NSUN2 knockdown inhibited these processes in vitro and in vivo." (PMID 32708015, 2020). "Taken together, these results indicated that expression of NSUN2 was associated with many key clinical features of breast cancer." (PMID 27447970, 2017). "The development of breast cancer is generally associated with hormone receptor levels, and therefore, we further examined the relationship between NSUN2 expression and ER status in breast cancer tissues." (PMID 27447970, 2017). "The hypo-expression of NSUN2 were observed in the breast cancer, which may cause the low m5C level on mRNA." (PMID 35456483, 2022). "Additionally, we show that NSUN2 expression was associated with estrogen receptor (ER) or progesterone receptor (PR) and Ki-67 in breast cancer." (PMID 27447970, 2017). "A more detailed pan-cancer analysis has determined that expression of several RNMTs, including NSUN2, had positive correlations between DNA copy number and mRNA expression and was associated with higher grade aggressive subtypes and poor prognosis in breast cancer patients." (PMID 32708015, 2020). "However, the functional role of NSUN2, mechanism of NSUN2 overexpression and its association with clinicopathologic features in breast cancer remain unclear." (PMID 27447970, 2017). "Bioinformatics analysis of the knockout datasets revealed decreased stoichiometry of Type I m5C sites, confirming that NSUN2 demonstrates a key m5C writer in breast cancer cells." (PMID 40555775, 2025). "In breast cancer cells and tissues, hypomethylation of NSUN2 DNA results in overexpression of NSUN2 mRNA and protein." (PMID 40370440, 2025). "In prostate, liver, colon, and breast cancer (BC) cells, as well as melanoma, glucose binds to the N‐terminal region of methyltransferase NSUN2, promoting its oligomerization and activation." (PMID 39802639, 2025). "Upregulation of NSUN2 promotes proliferation, migration, and invasion of breast cancer cells, while NSUN2 knockout inhibits these processes." (PMID 40370440, 2025). "Our results challenge this notion indicating a potential multifaceted role of NSUN2-mediated m5C methylation in breast cancer development and progression." (PMID 40555775, 2025). "Further catalysis-independent functions of Nsun2 have been previously reported, such as restoring mitotic spindle integrity in a breast cancer cell line or rescuing translation defects in NSUN2-defective human dermal fibroblasts." (PMID 41099711, 2025). "NSUN2, an m5C methyltransferase, has been shown to play a significant role in cancer progression in various cancers, including lung, hepatocellular, and breast cancers." (PMID 40234937, 2025). "The m5C methyltransferase NSUN2 is overexpressed in various tumors, such as breast cancer and colorectal malignancies." (PMID 39473440, 2024). "NSUN2 knockdown inhibited cell proliferation in NSUN2-overexpressing breast cancer and in MYC-driven squamous cell carcinoma." (PMID 37612540, 2023). "For example, the m5C methyltransferase NOP2/Sun RNA methyltransferase 2 (NSUN2) is overexpressed in breast cancer and is correlated with cancer development and progression." (PMID 37612540, 2023). "The expression of NSUN2 is upregulated in major gynecologic neoplastic diseases, it is also elevated in breast cancer and head and neck neoplasms." (PMID 37183262, 2023). "Among these results, cytosine located in gene PTPN2 (chromosome 18: 12789928), which is a tumor suppressor gene with a low expression ratio in breast cancer, was a putative site regulated by NSUN2 and YBX1." (PMID 35456483, 2022).